CDO1 (cysteine dioxygenase type 1)
Diseases named in the same sentence as CDO1 in open-access papers (continued):
Sharing a sentence is not in itself a finding about the gene and the disease.
cancer (continued). "In conclusion, our data implicates cancer-specific methylation and silencing of CDO1 as a common inactivation event in human carcinogenesis." (PMID 23028699, 2012). "Downregulation of CDO1 mRNA and protein levels were observed in cancer cell lines and tumors derived from these tissue types." (PMID 23028699, 2012). "We observed frequent promoter methylation and downregulation of CDO1 in multiple types of human cancer." (PMID 23028699, 2012). "Conversely, an increase of CDO1 in tumors was observed in less than 20% of patients with these types of cancer." (PMID 23028699, 2012). "The mRNA expression of CDO1 was silenced in all cancer cell lines tested but re-activated by the demethylating agent, 5-Aza-dC." (PMID 23028699, 2012). "Basal expression of CDO1 was barely detectable in cancer cell lines but stronger expression was observed in HEK293 and weakly in MCF-12A cell lines." (PMID 23028699, 2012). "In this study, we describe the identification of CDO1 promoter methylation, a specific marker for multiple types of human cancer." (PMID 23028699, 2012). "A mutation in the CDO1 gene (115170091G>C) has been found in a xenograft of metastatic CRC (liver metastasis, cancer stage IV)." (PMID 23028699, 2012). "We then examined the transcriptional level of CDO1 by RT-PCR and qRT-PCR analyses in cancer cell lines derived from breast, esophagus, lung, bladder, and stomach, and in non-tumorigenic cell lines (HEK293 and MCF-12A)." (PMID 23028699, 2012). "Given that DNMT3L can inhibit methylation and promote expression of CDO1, we hypothesized that its anti-cancer role might be mediated through CDO1." (PMID 38308276, 2024). "By compiling the current knowledge about apoptosis, ferroptosis, and the role of Cdo1, this review suggests possibilities for how the mild anticancer role of Cdo1 could be harnessed in new cancer therapies." (PMID 38672271, 2024). "In cancer cells, methylation is the most common variant of Cdo1, and although it is not sufficient to make cells cancerous, the presence of this variant can exacerbate the progression of cancer." (PMID 38672271, 2024). "If this hypothesis is true, CDO1, as a downstream regulatory gene, is also expected to exhibit anti-cancer functions." (PMID 38308276, 2024). "Therefore, upregulating Cdo1 in cancer cells is likely to assist the effect of major chemotherapeutic agents." (PMID 38672271, 2024). "Last, it has been mentioned in many cancer-related studies that Cdo1 expression is tightly controlled by promoter methylation, and hypermethylation of the Cdo1 promoter will lead to transcriptional inactivation and silencing of the Cdo1 gene." (PMID 38110408, 2023). "The analysis revealed down‐regulation of CDO1 expression in 17 types of human cancers including BC." (PMID 37740473, 2023). "CDO1 can regulate reduced glutathione and ROS levels of cancer cells to regulate ferroptosis." (PMID 36313765, 2022). "CDO1, a tumor suppressor gene, plays a role in the oxidative stress response of cancer cells." (PMID 34620221, 2021). "Moreover, cancer patients with CDO1 gene hypermethylation showed suppressed expression of CDO1 protein in immunohistochemistry." (PMID 30934021, 2019). "More work is needed to understand whether high intracellular CYS levels are a vulnerability of CDO1-silenced cancer cells as a consequence of these mechanisms, or whether there is an advantage to high intracellular CYS." (PMID 31107239, 2019). "Furthermore, in comparison of the CDO1 TaqMeth V between the two cancers, TaqMeth V was significantly higher in SBC up to Stage II compared with CRC." (PMID 30677088, 2019). "CDO1 functions as a tumor suppressor gene in various cancer cells." (PMID 30677088, 2019). "This allows cancer cells to grow more rapidly, and may explain why human tumors generally evolve to shut down CDO1." (PMID 31107239, 2019).
cancer (continued). "The aim of our study is to elucidate whether DNA methylation of the promoter region of the cancer-specific methylation gene, cysteine dioxygenase 1 (CDO1), contributes to the carcinogenic process in SBC." (PMID 30677088, 2019). "The limitation of CYS availability by CDO1 suggests that this enzyme may antagonize NRF2-dependent processes in cancer." (PMID 31107239, 2019). "Relationship with TaqMeth V of CDO1 and clinicopathological factors at cancer tissue." (PMID 29746493, 2018). "Immunostaining for CDO1 stained the cytoplasm of gland epithelial cells and cancer cells." (PMID 29746493, 2018). "The aim of our study is to elucidate whether the promoter DNA methylation of the cancer-specific methylation gene, cysteine dioxygenase 1 (CDO1), contributes to the carcinogenic process in CRC." (PMID 29746493, 2018). "Promoter DNA methylation of the CDO1 gene was, for the first time, proven to be cancer-prone in primary GBC, and it could be a useful biomarker independent of stage in primary GBC." (PMID 29161283, 2017). "The methylation of the CDO1 promoter region that was assayed in the current study was originally identified by robust screening of a pharmacological unmasking microarray that was carried out to explore cancer-prone methylation." (PMID 25469504, 2014). "Of these genes, the cancer-prone genes that was most frequently methylated in primary CRC was CDO1." (PMID 25469504, 2014). "Also, the methylation levels of two CpG sites in TSS200 of two tumor-suppressor genes (MIR34B and CDO1) were corrected, and some cancer samples showed almost complete methylation." (PMID 24312652, 2013). "Sensitivity and specificity of CDO1 methylation in multple types of human cancer." (PMID 23028699, 2012). "If epigenetic silencing of the CDO1 gene is responsible for enhanced aerobic glycolysis and mitochondrial dysfunction in human cancer, H2S may be a key molecule to activate the glycolytic pathway and accelerate mitochondrial dysfunction." (PMID 23028699, 2012). "Detection of CDO1 methylation levels in stool and/or plasma DNA may prove value of the gene in the diagnosis and monitoring of cancer patients." (PMID 23028699, 2012). "In addition, 5-Aza-dC treatment reactivated the CDO1 expression in the majority of cancer cell lines (exceptions were A549 and H1828), indicating that transcriptional expression of CDO1 tightly correlates with promoter methylation." (PMID 23028699, 2012). "Thus, further studies are worthwhile to elucidate whether ferroptosis mediated by the p73β-CDO-1 axis can be explored for cancer therapy." (PMID 36631448, 2023). "Notably, CDO1 promoter methylation is common across multiple cancer types raising the possibility that CDO1 antagonizes the proliferation or viability of other cancers through similar mechanisms." (PMID 31107239, 2019). "Moreover, since CDO1 methylation is universally found in other cancers, this technique may be a broadly applicable method for cancer detection by using blood." (PMID 25469504, 2014). "Thus, CDO1 is downregulated in multiple human cancers, particularly in cancers from female organs." (PMID 23028699, 2012). "Liquid biopsy-based DNA methylation testing, particularly targeting the cysteine dioxygenase type 1 (CDO1) gene promoter, has emerged as a promising approach for early cancer detection." (PMID 41602411, 2026). "However, no study has found that silencing mutations in Cdo1 alone can cause cancer." (PMID 38672271, 2024). "Furthermore, it is worth mentioning that due to the role of Cdo1 in enhancing apoptosis and cell cycle arrest, but not inducing apoptosis or cell cycle arrest, it is suggested that Cdo1 mutation cannot be the driver mutation leading to cancer." (PMID 38672271, 2024). "As expected, significantly more methylated epialleles of SOX17, CDO1, TAC1, and HOXA7 were detected in cancer patients compared to the benign group." (PMID 37039321, 2023).
cancer (continued). "CDO1 has been demonstrated to decrease the intracellular level of GSH, thus enhancing ROS generation in cancer." (PMID 35280684, 2022). "Two hypermethylated genes, namely, cysteine dioxygenase type 1 (CDO1) and zinc finger protein 454 (ZNF454), in patients with EC were identified from The Cancer Genome Atlas database." (PMID 35574348, 2022). "The promoter hypermethylation of CDO1, TAC1, HOXA7, and SOX17 were detected more frequently in the plasma of cancer patients compared with controls." (PMID 32138766, 2020). "Consistent with DNA methylation profiles in plasma, methylation of CDO1, TAC1, SOX17, and HOXA7 were detected more frequently in patients with cancer compared with controls." (PMID 32138766, 2020). "The methylation detection rate of CDO1, TAC1, SOX17, and HOXA7 were significantly higher in cancer group than in the benign group (p < 0.001)." (PMID 32138766, 2020). "In the present study, higher methylation frequencies of CDO1, TAC1, HOXA7, and SOX17were also observed in the plasma of cancer patients." (PMID 32138766, 2020). "Cancer specificity and sensitivity of CDO1 methyaltion was proven to be equal to those of either SEPT9 or Vimentin methylation in CRC, where the AUC of the ROC curve to differentiate cancer tissues from the corresponding normal mucosa was 0.96." (PMID 25469504, 2014). "Cdo1 can promote ferroptosis based on the current study, but ferroptosis has negative aspects to the body other than cancer." (PMID 38672271, 2024). "If, in cancer, the expression of these ion channels is reduced or dysfunctional, intracellular Ca2+ can be reduced, and GPX4 function is preserved, which counteracts GSH depletion by Cdo1." (PMID 38672271, 2024). "In some cancer cells, Cdo1 expression is promoted, but this promotion still fails to prevent carcinogenesis." (PMID 38672271, 2024). "Thus, by silencing CDO1, NRF2-addicted cancer cells maintain a large intracellular pool of cysteine for the glutathione synthesis, resulting from the increased cysteine uptake by xCT and decreased cysteine decomposition." (PMID 32112372, 2020). "Moreover, an alternative pathway of cysteine catabolism, which is mediated by CDO1, has been shown to be inactive in NRF2-addicted cancer cells due to DNA methylation at the CDO1 locus." (PMID 32112372, 2020). "Immunostaining for CDO1 protein confirmed its localization in the cytoplasm of non-cancerous gastric mucosa gland cells (data not shown) or cancer cells harboring low value of CDO1 gene methylation (L group)." (PMID 30934021, 2019). "Our findings indicated that TaqMeth V of CDO1 in CRC was 34.8 in cancer tissue and 4.3 in NAM, and we estimated that the cut-off value of CDO1 TaqMeth V that could be used to differentiate cancer tissue from NAM was 15.6." (PMID 29746493, 2018). "In our results, a high frequency of CDO1 down-regulation (>80%) was observed in female cancer patients, but not in male patients (<40%)." (PMID 23028699, 2012). "Additionally, CDO1 was identified as a target gene of DNMT3L and also exhibits anti-cancer effects." (PMID 38308276, 2024). "This indicates that there is an opportunity for therapeutic intervention by targeting CDO1 in particular cancer contexts in which CDO1 silencing is not occurring as it was described that CDO1 silencing by methylation was occurring preferentially in KEAP1-mutated cases in NSCLC." (PMID 38247476, 2023). "We then attempted to investigate whether the anti-proliferation role of CDO1 relied on its enzyme activity, as some enzymes have been documented to exert non-canonical functions in cancers." (PMID 36526626, 2022). "However, CDO1 was not differentially expressed between 13 pairs of normal tissues and cancer tissues." (PMID 34246261, 2021). "Correlations of RMVs between plasma samples and cancer tissues were found for CHFR (|r| = 0.458, p < 0.001), but not for SOX11 (|r| = 0.010, p = 0.94) and CDO1 (|r| = 0.011, p = 0.93)." (PMID 40666491, 2025).
cancer (continued). "We first compared methylation abnormality of the CDO1 between SBC tissue and small intestine non-cancerous mucosa by using the TaqMeth V. Significantly high CDO1 methylation abnormality was observed in the cancer tissue, and a TaqMeth V = 4.09 was obtained as the cutoff value." (PMID 30677088, 2019).
adenocarcinoma (2 papers, 2019 to 2024). A common cancer characterized by the presence of malignant glandular cells. "SOX17, TAC1, CDO1, HOXA9 and ZFP42 were the 5 genes that were identified in the Cancer Genome Atlas (TCGA) with highly prevalent DNA methylation in lung squamous and adenocarcinoma, but not in normal lung tissue." (PMID 38315228, 2024).
infection (2 papers, 2019 to 2020). The state of being infected such as from the introduction of a foreign agent such as serum, vaccine, antigenic substance or organism. "The genes ABHD8, CDO1, RNF125, cell surface hyaluronidase-like, and gopAga1_00017729 were upregulated in medium and severely infected animals relative to control, indicating these may be biomarkers of infection." (PMID 32846428, 2020). "To examine whether Cdo1 mediates CYS metabolism to CSA and HTAU, and whether this limits the use of CYS for GSH synthesis, we deleted Cdo1 with CRISPR/Cas9, followed by infection with empty or Cre expressing adenovirus to generate Cdo1-deficient, isogenic Keap1WT and Keap1R554Q MEFs." (PMID 31107239, 2019).
neurodegenerative disease (1 paper, 2024). A disorder of the central nervous system characterized by gradual and progressive loss of neural tissue and neurologic function. "CDO1’s regulation of cysteine metabolism significantly impacts metabolic and neurodegenerative diseases." (PMID 38415056, 2024).
CDO1 also shares sentences with these, for which no sentence is quoted: bladder cancer (2 papers); stomach cancer (2); acute myeloid leukemia (1); astrocytoma (1); brain cancer (1); breast adenocarcinoma (1); cholangiocarcinoma (1); chronic hepatitis (1); colorectal adenoma (1); digestive system cancer (1); Endometrial Intraepithelial Neoplasia (1); endometrioid adenocarcinoma (1); isolated sulfite oxidase deficiency (1); kidney tumor (1); metabolic disorders (1); myelodysplastic syndrome (1); osteosarcoma (1); Parkinson disease (1); renal cell carcinoma (1); rheumatoid arthritis (1); Sézary syndrome (1); small bowel tumors (1); small cell lung carcinoma (1); Wilms tumor (1).